IL18R1 (interleukin 18 receptor 1)
Description:
Within the IL18 receptor complex, responsible for the binding of the pro-inflammatory cytokine IL18, but not IL1A nor IL1B. Involved in IL18-mediated IFNG synthesis from T-helper 1 (Th1) cells. Contributes to IL18-induced cytokine production, either independently of SLC12A3, or as a complex with SLC12A3 (By similarity).
Synonyms: IL-1Rrp; IL-18R-alpha; IL-18Ralpha; CD218a; IL1RRP; IL-18R; CDw218a; IL18RA; IL18Ralpha2
Tractability: Antibody: its Gene Ontology location is reachable by antibodies, with high confidence; UniProt predicts a signal peptide or a membrane-spanning region. PROTAC: ubiquitination databases record sites on it; its protein half-life has been measured. Other modalities: a drug acting on it is in phase 2 or 3 trials.
Gene: Protein-coding gene on chromosome 2 (102,311,529 to 102,398,777, forward strand). Ensembl gene ENSG00000115604.
Subcellular location: Membrane
Subcellular location (Human Protein Atlas): Mitochondria
Pathways (Reactome):
Immune System: Interleukin-18 signaling; Interleukin-37 signaling
Gene Ontology:
Molecular function: interleukin-18 binding; interleukin-18 receptor activity; protein binding; signaling receptor activity; interleukin-1 receptor activity; NAD+ nucleosidase activity, cyclic ADP-ribose generating
Biological process: interleukin-18-mediated signaling pathway; positive regulation of T-helper 1 cell cytokine production; positive regulation of type II interferon production; adaptive immune response; cellular response to lipopolysaccharide; defense response to Gram-positive bacterium; immune response; negative regulation of cold-induced thermogenesis; signal transduction; T-helper 1 cell differentiation; positive regulation of non-canonical NF-kappaB signal transduction
Cellular component: interleukin-18 receptor complex; membrane; cell surface; plasma membrane
Genetic constraint (gnomAD): Loss-of-function variants: 20 observed, 25.15 expected, observed/expected ratio (o/e) 0.8, 90% interval 0.56 to 1.15. The upper end of that interval is the gene's LOEUF score, 1.15, which puts it in group 5 of 6, group 1 being the genes least tolerant of losing a copy. Missense variants: 350 observed, 421.8 expected, observed/expected ratio (o/e) 0.83, 90% interval 0.76 to 0.91. Synonymous variants: 154 observed, 153.63 expected, observed/expected ratio (o/e) 1, 90% interval 0.88 to 1.15.
Homologues: Orthologues: macaque IL18R1 (96% identical), chimpanzee IL18R1 (80% identical), rabbit IL18R1 (74% identical), dog IL18R1 (73% identical), pig IL18R1 (66% identical), rat Il18r1 (65% identical), mouse Il18r1 (63% identical), guinea pig IL18R1 (61% identical), tropical clawed frog il18r1.1 (34% identical). Paralogues in human: IL1RAPL2 (29% identical), IL1RAP (28% identical), IL1RAPL1 (26% identical), IL18RAP (25% identical), IL1R1 (25% identical), IL1RL1 (24% identical), IL1RL2 (24% identical), SIGIRR (14% identical), LAG3 (13% identical), IL1R2 (12% identical).
Diseases named in the same sentence as IL18R1 in open-access papers:
IL18R1 is named in the same sentence as 163 diseases in open-access papers, as found by Europe PMC text mining. Sharing a sentence is not in itself a finding about the gene and the disease. The quoted sentences say what the papers report.
asthma (43 papers, 2009 to 2026). "have studied the relationship between IL18R1 gene polymorphisms and childhood asthma in the Turkish population, and discovered that IL18R1 c." (PMID 39847405, 2025). "IL18R1, a key member of the IL-1 receptor family, can activate NF-κB and is linked to acute mountain sickness and asthma." (PMID 41385345, 2025). "In particular, type-I IFN stimulation, specifically IFNα, induced the upregulation of the pro-inflammatory gene IL18R1, whose expression was associated with asthma severity in human bronchial epithelial biopsy and in bronchial alveolar lavage." (PMID 36354438, 2022). "In asthma, genome‐wide association studies have shown that interleukin‐18 (IL‐18) receptor 1 gene (IL‐18R1) and sputum IL‐18 are increased during exacerbations." (PMID 34194747, 2021). "Our computational identification is supported by numerous previous studies linking epithelial IL-18R1 expression to more SA and the consistent linkage of single nucleotide polymorphisms in the IL-18R1 genetic locus to asthma." (PMID 34591794, 2021). "Large genome‐wide association studies have consistently identified IL‐18R1 as one of the loci most strongly associated with asthma." (PMID 34194747, 2021). "IL-18R1 is found in the asthma susceptibility locus on chromosome 2q12 and has been linked to asthma risk in genome-wide association studies." (PMID 34591794, 2021). "A strong association between a single-nucleotide polymorphism (SNP) located in IL18R1 and asthma and atopic phenotypes has been recently observed." (PMID 23515576, 2013). "A GWA study of eosinophil counts with follow-up testing in asthma case-control studies identified variants near IL1RL1/IL18R1 and IL33 as being associated with asthma." (PMID 23028483, 2012). "Recently, polymorphisms in IL18 receptor 1 (IL18R1) have been reported to be associated with asthma and bronchial hyperresponsiveness in the European population." (PMID 19335888, 2009). "A significant association has been found between IL18R1 gene polymorphisms and asthma." (PMID 39847405, 2025). "An association between asthma and a SNP in the IL18R1 region is reported." (PMID 30990817, 2019). "Data from the Severe Asthma Research Program (SARP) cohort using machine learning validated IL18R1 protein expression in lung tissue and identified downstream NF-κB and activator protein 1 (AP-1) activity." (PMID 39554494, 2024). "Our approach identified heightened IL-18R1 expression in a subset of patients with asthma with impaired lung function and frequent exacerbations." (PMID 34591794, 2021). "Another large-scale GWAS for asthma has identified six asthma-susceptible loci, including IL1RL1/IL18R1, SMAD3, ORMDL3/GSDM, IL-33, IL2RB, and HLA-DQ." (PMID 34946955, 2021). "IL18R1 and IL1RL1 have been shown in many studies to have variants associated with asthma as well as having altered expression profiles in asthmatic subjects." (PMID 35386986, 2021). "We observed correspondence between IL-18R1 expression, mixed Type-1 (T1) and T2 inflammatory state, and clinical disease severity in both asthma cohorts." (PMID 34591794, 2021). "Harmful effects of IL-18R1 on asthma and celiac disease were also identified, but only in some sensitivity analyses where we adopted stricter thresholds for the genetic instruments." (PMID 34878845, 2021). "We validated IL18R1 protein expression in lung tissue and identified downstream NF-κB and AP-1 activity, supporting IL-18 signaling in severe asthma pathogenesis and highlighting this approach for gene and pathway discovery." (PMID 34591794, 2021). "One of the most replicated asthma-associated genetic signals is the chromosome 2q12 locus, containing the IL-1 receptor like 1 (IL1RL1), IL18R1, and IL-18 receptor accessory protein (IL18RAP) genes." (PMID 32324168, 2020). "They observed associations with asthma, particularly childhood-onset asthma, at multiple loci (ORMDL3/GSDMB, IL1RL1/IL18R1, HLA-DQ, IL33, SMAD3, and IL2RB)." (PMID 23028483, 2012).
asthma (continued). "In the same year, another candidate gene association study documented significant genetic association of the gene cluster containing IL1RL1, IL18R1 and IL18RAP with asthma and atopy in a Dutch population." (PMID 21629437, 2010). "As another example, IL1RL1 pQTLs colocalised with IL1RL1, IL18R1 and IL18RAP eQTLs detected in multiple cell types with direct effects on the immune system (e.g. T-cells); these variants were associated with asthma and allergic reactions in the PheWAS." (PMID 38565889, 2024). "Polymorphisms in IL18R1, a gene in tight LD with IL1RL1, were associated with asthma, atopic asthma and airway hyper-responsiveness using a candidate gene approach in a Danish population and the association consistently replicated in two other European populations." (PMID 21629437, 2010). "Therefore, IL18R1 is a good candidate for asthma, and further replication studies are required to determine the causal variants." (PMID 19335888, 2009). "IL-18R1 was negatively correlated to FEV1 in both the SARP and Immune Mechanisms of Severe Asthma (IMSA) cohort." (PMID 39554494, 2024). "This previous study identified genes on chromosomes 2 (IL1RL1/IL18R1), 6 (HLA-DQ), 9 (IL33), 15 (SMAD3), 17 (ORMDL3/GSDMB), and 22 (IL2RB) correlated with asthma." (PMID 32512817, 2020). "Prior evidence suggests that expression of IL-18 pathway components, specifically IL-18R1, differs between those with asthma and those without." (PMID 34591794, 2021). "We validated IL-18R1 expression and downstream transcription factor (TF) activity at the protein level in the SARP cohort, as well as in patients who underwent video-assisted thoracoscopic surgery (VATS) lung biopsy for severe, treatment refractory asthma." (PMID 34591794, 2021). "Given these suggestive RNA data, we validated the protein expression of IL-18R1 using a separate cohort of VATS lung biopsies in patients with extremely severe asthma who underwent the procedure to rule out confounding diagnoses such as eosinophilic granulomatosis with polyangiitis." (PMID 34591794, 2021). "Thus, the asthma loci IL33, IL1RL1/IL18R1, RORA, and IL13 previously identified by GWAS belong to the same pathway, and could modify airway inflammation and interleukin responses that are crucial for the development of asthma." (PMID 23565190, 2013). "A very recent GWA study of severe asthma in Europeans found strong evidence for two previously established loci (ORMDL3/GSDMB and IL1RL1/IL18R1) in patients with severe asthma but did not identify any novel loci." (PMID 23028483, 2012).
COVID-19 (16 papers, 2020 to 2026). A disease caused by infection with severe acute respiratory syndrome coronavirus 2. "It is worth noting that activation of the IL18/IL18R1/HIF-1 signaling axis was found to mediate an increased risk of peripheral vascular diseases such as aneurysms and atherosclerosis after COVID-19." (PMID 36851546, 2023). "IL-18R1 was also increased in splenic tissue in addition to peripheral blood in severe COVID-19 and has a role in B-cell expansion." (PMID 34710339, 2022). "The proteins overlapping with the enriched “B-cell Receptor Signaling Pathway (WP23),” JUN, HCLS1, PIK3AP1, and CRKL, were all increased in abundance in the COVID-19 spleen tissue, in addition to IL-18R1." (PMID 34710339, 2022). "In this study, using the same patient cohorts, we found that the gene encoding for the alpha chain of the IL-18 receptor, IL18R1, was also highly expressed in patients who succumbed to severe A(H7N9) infection, as well as in patients with life-threatening COVID-19, RSV and MIS-C." (PMID 41285788, 2025). "We found inverse correlations between CD84 with OLAH and IL18R1 levels in our A(H7N9) cohort, and in hospitalised COVID-19 patients across respiratory disease severities." (PMID 41816098, 2026). "Our IL18R1 transcriptomics data were further verified at the protein level and demonstrated markedly elevated surface IL-18Rα expression in patients hospitalized with influenza A, influenza B, RSV and COVID-19 on CD8 T cells." (PMID 41285788, 2025). "In comparison to samples from a cohort of healthy individuals that were used as controls, IL18R1 expression was significantly elevated in patients hospitalized with COVID-19 with no or minimal respiratory dysfunction (P = 0.019)." (PMID 41285788, 2025). "Mostly, markers of inflammation such as IL-6, IL-10, CXCL10 (also known as IP10), CXCL11, CCL2, CCL7, CCL8, PD-L1, and IL-18R1 were increased at the early stage of COVID-19 in ICU patients compared to non-ICU ones." (PMID 35269564, 2022). "In fact, from the group comparison of COVID-19 vs. non-COVID-19, the authors identified 14 specific inflammatory proteins that can be related to SARS-CoV-2 infection, namely CXCL5, CXCL10, CXCL11, Gal-9, IL-18, IL-18R1, IFNγ, LIF-R, MCP-2, MCP-3, MERTK, MMP-1, PD-L1, and TNF." (PMID 35269564, 2022).
colitis (15 papers, 2013 to 2025). Inflammation of the colon. "Further studies showed that deletion of IL-18R1 in intestinal epithelial cells inhibited mucosal damage and colitis in a mouse model of ulcerative colitis." (PMID 32719716, 2020).
diabetes (14 papers, 2010 to 2026). "Interleukin-18 receptor 1 (IL-18R1) showed the strongest positive association with diabetes (OR = 2.09 [95%CI: 1.61, 2.73] per SD increase), while TWEAK showed the strongest inverse association with diabetes (OR = 0.70 [95%CI: 0.56, 0.89])." (PMID 38643166, 2024). "Interleukin-18 receptor 1 predicted higher risk and angiopoietin-1 predicted lower risk among patients with diabetes." (PMID 37816758, 2023). "In searching for potential mechanisms underlying the observed association between gut bacteria and diabetes, our results suggested that alterations in several circulating immune and proinflammatory proteins, especially IL-18R1 and OPG, might play a role." (PMID 38643166, 2024). "In mediation analyses, several proteins, especially interleukin-18 receptor 1 and osteoprotegerin, IMP and PAGln partially mediate the observed bacterial genera–diabetes associations, particularly for those of Adlercreutzia and Escherichia." (PMID 38643166, 2024). "We also found that diabetes was related to increased expression of nine proteins, IL-18R1, CCL11, CDCP1, OPG, HGF, TGF-α, CCL20, IL-6 and FGF-21." (PMID 34385358, 2021). "Specifically, Pstpip1, Il18r1, Sult2a1 overlapped the QTLs of “Non-insulin dependent diabetes mellitus (Niddm)”." (PMID 21124896, 2010). "Moreover, several proteins, especially IL-18R1 and OPG, and microbial derived metabolites, including IMP and PAGln, significantly mediated the associations between identified gut bacteria and diabetes, both individually and in combination." (PMID 38643166, 2024). "For another eight biomarkers (TNFβ, GDNF, IL-18R1, LIF-R, CD244, CD6, FGF-5, IFNγ), a significant interaction by diabetes type was observed." (PMID 39799156, 2025). "Notably, associations of Ruminococcus, Adlercreutzia, and Escherichia with diabetes were mediated considerably by multiple inflammatory proteins led by OPG, IL-18R1, and HGF." (PMID 38643166, 2024). "However, a cohort study reported that melioidosis patients with a preadmission diagnosis of diabetes treated with glibenclamide had decreased levels of TNF-α, IL-18-R1, and IL-8 and lower in-hospital mortality compared to patients without diabetes." (PMID 28740332, 2017). "Notably, IL-18R1 is the receptor of proinflammatory cytokine IL-18, and overproduction of IL-18 has been noted as a proxy biomarker for overall inflammation and immune activation in HIV infection and metabolic-inflammatory diseases (e.g., diabetes and non-alcoholic fatty liver diseases (NAFLD))." (PMID 38643166, 2024).
atopic dermatitis (10 papers, 2018 to 2025). "The level of circulating IL-18R1 was identified as a mediator for the increased risk of atopic dermatitis associated with higher levels of PC (18:1_20:2), accounting for a mediation proportion of 9.07%." (PMID 38909247, 2024). "The top IL18R1 SNP rs2001461 with an iHS CEU score of 4.544 was associated with blood protein (IL18R1) measurement, while two other SNPs were associated with serum ST2 (the IL1RL1 gene product) measurement (rs1420103) and atopic eczema (rs6419573)." (PMID 32895400, 2020). "Several loci were disease-specific, such as Filaggrin (FLG) for atopic dermatitis, or a SNP near IL18R1, where the effect allele was increased in asthma and hayfever, but not atopic dermatitis." (PMID 31921716, 2019).
Obesity (10 papers, 2015 to 2026). Accumulation of substantial excess body fat. "Collectively these results are also in agreement with a divergence in diet induced thermogenesis between Il18 and Il18r1-KO mice, which might justify their different susceptibility to dietary obesity." (PMID 26656097, 2015). "We saw in the immunometabolism component that obesity and known related clinical variables associated with elevated levels of cytokines TRANCE, CCL4, IL18R1, CCL3 and FGF21, for which known links to obesity were discussed." (PMID 33204460, 2020). "Feed efficiency differences depending on the dietary fat amount suggested that Il18r1-KO were less obesity-prone than Il18-null mice, through either divergence in substrate utilization and/or energy expenditure." (PMID 26656097, 2015). "Understanding of the molecular mechanisms by which ablation of IL18R1 exerts its effects may provide a novel therapeutic approach to treat obesity." (PMID 26656097, 2015). "In summary our data show that lack of Il18 but not Il18r1 in mice led to an increased susceptibility to dietary obesity." (PMID 26656097, 2015). "Lack of Il18 but not Il18r1 in mice led to increased susceptibility to dietary obesity." (PMID 26656097, 2015).
autoimmune disease (8 papers, 2018 to 2024). A disorder resulting from loss of function or tissue destruction of an organ or multiple organs, arising from humoral or cellular immune responses of the individual to their own tissue constituents. "IL-18 activity has previously been linked to several autoimmune diseases, and preventing IL-18 from binding to IL-18R1 reduces the risk of inflammatory diseases." (PMID 34878845, 2021). "Many of these genes have either known roles in Treg differentiation, stability and function (CD48, IL6ST, EZR, ELMO1, IL18R1), or altered expression in human Treg in autoimmune disease (SLAMF1, ANKRD55, TAGAP)." (PMID 35773720, 2022). "Taken together, the evidence suggests a pro-inflammatory role for IL1RL1 and IL18R1 in autoimmune disease." (PMID 32719716, 2020). "Genetic ablation of IL18R1 or blockade of IL-18 receptor signaling could protect mice from autoimmune disease.Three SNPs (rs12999364, rs12987977, and rs4851569) located in the IL1RL1–IL18R1 region were associated with ocular manifestations in Chinese BD patients." (PMID 38983559, 2022). "Comparison of rules for each disease revealed that TLR3, TLR5, IL18, IL18R1, and IL1R1 genes occurred in rules for all studied diseases, showing good discriminant power among studied autoimmune diseases as visualized by the Andrews curves." (PMID 31396542, 2019).
atherosclerosis (7 papers, 2009 to 2023). A disease characterized by the build-up of fatty material and calcium deposition in the arterial wall resulting in partial or complete occlusion of the arterial lumen. "This suggested that AC007278.2 and IL18R1 may be associated with atherosclerosis and cardiovascular complications, which may provide a novel field in understanding the disease progression of AMI, MF, and HF." (PMID 34336943, 2021). "IL18R1 and IL18RAP genes code for two receptors of the IL-18 cytokine that has been found associated with atherosclerosis and its cardiovascular complications." (PMID 19473509, 2009). "In addition, the expression level of IL18R1 is significantly altered in systemic and arterial bed-dependent atherosclerosis plaques." (PMID 34336943, 2021). "The IL-18 cytokine, coded by interleukin 18 receptor 1 (IL18R1), has been found to be involved in atherosclerosis and cardiovascular complications." (PMID 34336943, 2021).
inflammatory bowel disease (7 papers, 2009 to 2025). A spectrum of small and large bowel inflammatory diseases of unknown etiology. "We demonstrated putative causal relationships between CD6 and IL18R1 with inflammatory bowel disease and between IL12B and Crohn’s disease." (PMID 32641083, 2020). "In addition, IL18R1 might be mainly involved in inflammatory bowel disease, PD-L1 (programmed death-ligand 1) expression, and hepatitis B, PD-1 (programmed cell death protein-1) checkpoint pathway in cancer and Th1/Th2 cell differentiation." (PMID 39847405, 2025).